TLR4 (toll like receptor 4)
Diseases named in the same sentence as TLR4 in open-access papers (continued):
Sharing a sentence is not in itself a finding about the gene and the disease.
atherosclerosis (continued). "Atherosclerosis-prone ApoE−/− mice with deficiency of TLR4 or MyD88 show attenuation in atherosclerosis development through decreased macrophage recruitment." (PMID 27795867, 2016). "Stimulation of TLR4 leads to activation of the NF-κB family of transcription factors, a key upstream regulator of atherosclerosis-associated inflammation." (PMID 26959822, 2016). "Further experimental evidence from loss-of-function animal models supports the role of TLR4 in atherosclerosis." (PMID 27795867, 2016). "The presence of a loss-of-function TLR4 Asp299Gly polymorphism in human subjects has been reported to be associated with a reduced risk of atherosclerosis." (PMID 27563891, 2016). "These pro-atherogenic effects are mediated by the cellular receptor for LPS, TLR4 and loss of this receptor in TLR4, ApoE double knockout mice results in reduced atherosclerosis." (PMID 27168152, 2016). "Toll like receptor 4 has been strongly implicated in driving atherosclerosis-associated inflammation." (PMID 26959822, 2016). "Despite that TLR4 plays a pathogenic role in atherosclerosis through its actions on endothelial cell activation and macrophage recruitment, its role in VSMC proliferation and migration and the precise mechanisms are still not well understood." (PMID 27563891, 2016). "ApoE−/− mice deficient in TLR4 have reduced atherosclerosis, which establishes that TLR activated pathways contribute to disease development." (PMID 27166190, 2016). "Polymorphisms of TLR4 have been associated with Crohn's disease, ulcerative colitis, asthma and atherosclerosis." (PMID 26442097, 2015). "The reduction of atherosclerosis in mice treated with these constructs was associated with a decrease in both TLR4 and MyD88 contents." (PMID 25830298, 2015). "The roles of the TLR4 signaling pathway in the processes underlying inflammatory vascular diseases including atherosclerosis, diabetes or pre-eclampsia have been reported." (PMID 25093580, 2014). "Mice deficient in TLR4 show reduced atherosclerosis proving that Toll-like receptor-dependent signaling participates in disease development." (PMID 25196434, 2014). "On the basis of the reports that 5-LO signaling is associated with multiple inflammatory conditions including atherosclerosis, our results provide an important insight into the mechanism of TLR4 signaling in the modulation of 5-LO expression in monocytes." (PMID 25116953, 2014). "These pathways are important in terms of sensing infection, but TLR4 is also associated with vascular inflammation and atherosclerosis." (PMID 24690886, 2014). "In contrast, ApoE(–/–) and TLR4(–/–) double-knockout mice were markedly more susceptible to atherosclerosis after oral infection with P. gingivalis, demonstrating an atheroprotective role for TLR4 in response to P. gingivalis infection." (PMID 24949459, 2014). "The recent association between bacterial infections and atherosclerosis has intensified the search for the biological functions of TLRs especially TLR4 in blood vessel formation." (PMID 25071774, 2014). "TLR4 has been shown to be an important factor responsible for triggering atherosclerosis and the associated cardiovascular diseases." (PMID 25116953, 2014). "Accordingly, mRNA expression of TLR-2 and TLR-4 in the aorta is associated with the severity of atherosclerosis and serum levels of inflammatory markers in hypercholesterolemic rabbits." (PMID 24901254, 2014). "The extent of atherosclerosis can be notably decreased in TLR4 deficiency mice, suggesting a direct role of TLR4 as one of oxLDL receptors in oxLDL-induce inflammatory response and in the pathophysiology of atherosclerosis." (PMID 24755612, 2014). "In particular, activation of TLR4 by specified ligands can provoke vascular inflammation linked to atherosclerosis." (PMID 25116953, 2014).
atherosclerosis (continued). "The common loss-of-function TLR4 polymorphism is associated with a decreased risk of carotid and femoral artery atherosclerosis and cardiovascular cause of death and reduced risk of acute coronary events, independent of other coronary risk factors." (PMID 24376657, 2013). "Toll-like receptor 4 (TLR4) recognizes pathogen-associated molecular patterns in some animals and has been shown to be closely associated with several diseases such as tumors, atherosclerosis, and asthma." (PMID 24025421, 2013). "In contrast to previous studies on TLR2, when ApoE−/− mice deficient in TLR4 were infected with P. gingivalis they were paradoxically more susceptible for developing atherosclerosis, presenting with increased levels of inflammatory Th17 cells." (PMID 23880853, 2013). "A considerable body of evidence has subsequently linked the TLR4 Asp299Gly and Thr399Ile SNPs with atherosclerosis." (PMID 23730203, 2012). "Mice deficient in MyD88 are less prone to atherosclerosis and patients with D299G polymorphism of TLR4 have reduced risk of this disease." (PMID 23305364, 2012). "The TLR4 SNPs Asp299Gly and Thr399Ile have also been associated with diseases other than atherosclerosis." (PMID 23730203, 2012). "Activation of TLR4 is generally considered to lead to pro-inflammatory effects in blood vessels and is linked to the development of septic shock and atherosclerosis." (PMID 21513697, 2011). "The first indication of a role for TLR4 in atherosclerosis came from the finding that C3H/HeJ mice - that hold a missense mutation of TLR4's cytoplasmic component - are resistant to atherosclerosis." (PMID 21526997, 2011). "These polymorphisms are reported to alter responsiveness to TLR4 activation and correlate with protection from atherosclerosis, CVD and the metabolic syndrome in some populations." (PMID 20814545, 2010). "The results of these small animal studies have been supported by population studies examining the development of atherosclerosis in humans with polymorphisms (Asp299Gly and Thr399Ile) in TLR4, which impair its ability to elicit an inflammatory response." (PMID 20676278, 2009). "Aerobic exercise has the potential to upregulate the level of miR-146a in serum, which may mitigate vascular tumor necrosis factor receptor-associated factor (TRAF) and TLR4 pathways, thereby attenuating vascular inflammation and damage in atherosclerosis." (PMID 40861271, 2025). "PF may inhibit the inflammatory response via the TLR4/MyD88/NF-κB pathway to attenuate the occurrence of atherosclerosis; therefore, the specific underlying mechanism warrants further study." (PMID 40815470, 2025). "The role of TLR4 in atherosclerosis is also supported by several loss-of-function animal models." (PMID 38445291, 2024). "Toll-like receptor 4 (TLR4) is linked with different stages of atherosclerosis." (PMID 38445291, 2024). "Furthermore, TLR4 has been implicated in psoriasis and related conditions such as Crohn’s disease, ulcerative colitis, and atherosclerosis." (PMID 39509434, 2024). "Activation of TLR4 has been associated with the onset and progression of atherosclerosis." (PMID 39453113, 2024). "TLR4 contribution to the vascular damage by activating inflammatory signalling pathways involving oxidative stress mechanisms, and its closely association with the pathogenesis of CVDs such as atherosclerosis and hypertension, have been described." (PMID 36937865, 2023).
atherosclerosis (continued). "An increase in the number of circulating TLR4-positive intermediate monocytes > 467.0 cells/μL was also associated with an increase of 3.95 times in the RR of polyvascular atherosclerosis progression (95% CI 1.62–9.66; p = 0.003) after adjusting for sex, age, and smoking." (PMID 37569579, 2023). "In this regard, it could be concluded that TLR4 inhibitors might be a novel treatment to prevent cardio-cerebrovascular events by decreasing the risk of atherosclerosis." (PMID 34580342, 2021). "Activation of the endothelial innate immune pathways of TLR2 and TLR4 is known to modulate pathways involved in endothelial permeability and coagulation that are associated with the initiation and progress of atherosclerosis, as well as with acute atherothrombotic adverse events." (PMID 34944024, 2021). "The contribution of TLR4 to the progression of atherosclerosis is supported by two studies showing that TLR4-deficient ApoE−/− mice have lower aortic lipid accumulation (70–80% reduction) and reduced levels of aortic atherosclerosis compared to the control mice." (PMID 35083304, 2021). "Macrophage treated with chia seed-treated adipocyte condition media effectively suppressed inflammatory cytokines (PAI-1, MCP-1, PGE-2 and TLR-4) linked with arterial vessels of cerebral, coronary and lower limb related immune disorders, such as atherosclerosis, stroke and thrombosis." (PMID 32235695, 2020). "We determined whether endotoxin levels and the presence of TLR4 polymorphisms are associated with markers of inflammation and atherosclerosis among South African CKD patients." (PMID 32649699, 2020). "The responsiveness of an individual to LPS via the TLR4 signaling cascades provides an efficient innate immunity, which offers initial benefit but portends chronic vascular damage and increased risk of future atherosclerosis." (PMID 32649699, 2020). "Similarly, the finding that ApoE-knockout mice deficient in TLR-4 have less atherosclerotic burden also supports the notion of a role of metabolic endotoxemia in atherosclerosis." (PMID 33505393, 2020). "Apart from immune cells, TLR4 is also well expressed in cells of the cardiovascular system, and its role in the processes underlying inflammatory vascular diseases such as atherosclerosis, hypertension, diabetes, and other vascular inflammatory pathologies is well reported." (PMID 31336567, 2019). "There is a significant decrease in the risk of atherosclerosis in patients with TLR4 mutation." (PMID 31007833, 2019). "However, the underlying mechanism atherosclerosis-related inflammation elicited by TLR4 activation in the context of this chronic stress is still unclear." (PMID 30881312, 2019). "Human cross-sectional studies showed that TLR4 is involved in monocyte activation of patients with accelerated forms of atherosclerosis, and the upregulation of TLR4 on human monocyte subsets is closely associated with coronary plaque vulnerability in patients." (PMID 31582899, 2019). "TLR2 and TLR4, subfamilies of TLRs, expressed in lesions, macrophages, dendritic cells, endothelial cells, and vascular smooth muscle cells, have been implicated in the pathogenesis of atherosclerosis." (PMID 30671470, 2018). "The presence of A allele could increase the chances of TLR4 activation and thus increased inflammatory response and atherosclerosis." (PMID 29922617, 2018). "Over the past years, TLR4 has been implicated in the pathogenesis of atherosclerosis." (PMID 30671470, 2018). "Also, TLR4 polymorphisms with attenuated receptor signaling are associated with decreased risk of atherosclerosis." (PMID 29649324, 2018).
atherosclerosis (continued). "A role for miR-146a in atherosclerosis is suggested by its ability to negatively regulate several pro-inflammatory factors that promote disease progression, including Toll-like receptor 4 (TLR4), IL-1 receptor-associated kinase 1 (IRAK1), and TNF receptor-associated protein factor 6 (TRAF6)." (PMID 29902229, 2018). "TLR4 is predominantly known for its role as an important mediator of innate immune response and has been implicated in the initiation, progression, and plaque destabilization stages of atherosclerosis." (PMID 28793055, 2017). "Variants in the gene encoding TLR4 may affect the development of atherosclerosis accompanied by an impaired signal transduction, but the responsible polymorphisms remain inconclusive." (PMID 28793055, 2017). "In TLR2−/− and TLR4−/− mice, atherosclerosis-associated inflammation was diminished." (PMID 27795867, 2016). "TLR4 and its agonists are associated with onset and progression of atherosclerosis." (PMID 27166190, 2016). "However, to further confirm the role of TLR4 ligand-induced IL-6 production in the pathogenesis of atherosclerosis, in vivo studies using TLR4-deficient mice should be conducted in the future." (PMID 27563891, 2016). "Therefore, studies on the mechanisms of negatively regulating TLR4-mediated signaling are pivotal for the cure of atherosclerosis-associated diseases." (PMID 26492242, 2015). "Studies have shown that TLR4/NF-κB signaling might be the important associated with inflammation and atherosclerosis." (PMID 25860573, 2015). "TLR4 is implicated in a different range of pathological processes associated with autoimmune diseases such as psoriasis, diabetic retinopathy, thrombosis, and inflammatory disorders including arthritis and atherosclerosis." (PMID 26613049, 2015). "Whilst not definitive, these experiments are consistent with the idea that hESC-EC will retain their TLR4-deficient phenotype in vivo, and supports our hypothesis that, through this property, they would be resistant to atherosclerosis." (PMID 24690886, 2014). "Circumstantial considerations that support a link between the metabolic syndrome and LPS signaling include the increased cardiovascular risk in patients with the metabolic syndrome and the positive association of TLR4 activity with atherosclerosis progression in mice and human beings." (PMID 25429291, 2014). "We have speculated that this may provide an advantage since TLR4 on endothelial cells is directly linked to atherosclerosis." (PMID 24690886, 2014). "TLR4 is associated with various diseases in animals, such as tumors, atherosclerosis, and asthma." (PMID 24025421, 2013). "Thus, TLR4 SNP +896 G + seems to determine a minor risk to develop atherosclerosis by decreasing pro-inflammatory signals and increasing anti-inflammatory cytokine production." (PMID 23391127, 2013). "Owens et al11 recently reported that deficiency of TLR4 or MyD88 reduced both angiotensin II (AngII)–induced atherosclerosis and AAA formation, indicating that innate immune signaling may contribute to the pathogenesis of AAA." (PMID 23537804, 2013). "This intriguing finding may help explain the contradictory studies regarding TLR4 SNPs and their association with atherosclerosis." (PMID 23730203, 2012). "Toll-like receptor 4 (TLR4) plays a key role in the activation of innate immune responses and has been implicated in the initiation, progression, and plaque destabilization stages of atherosclerosis." (PMID 22927710, 2012). "This mmLDL-induced and TLR4/Syk-dependent macropinocytosis is suggested to constitute an important mechanism of excessive lipid accumulation in macrophages, resulting in formation of lipid-laden macrophage foam cells, a hallmark of atherosclerosis." (PMID 22384232, 2012). "In addition, TLR4 can respond to endogenous damage-associated signals and give rise to sterile inflammation, a mechanism recently suggested for atherosclerosis and Alzheimer's disease." (PMID 21809339, 2011).
atherosclerosis (continued). "Interestingly, C3H/HeJ mice, which carry a missense mutation affecting the cytoplasmic portion of TLR4, are resistant to diet-induced atherosclerosis." (PMID 20652007, 2010). "In this line, also TLR4 has been found raised in areas with atherosclerosis plaque which were relatively close to suffer a separation from vascular wall, as well as it has been found how different polymorphisms in TLR4 may be associated with larger tendency to cardiovascular events." (PMID 37920579, 2023). "Interestingly, one of the bacteria involved in the pathogenesis of atherosclerosis, Porphyromonas gingivalis, which is associated with the development of periodontal disease, appears to induce activation of the NF-κB inflammatory pathway, in addition to TLR-4." (PMID 38139349, 2023). "Recently, many studies have shown that abnormal DNA damage induced by aging can activate inflammation via TLR4 and that TLR4 is crucial for the development of inflammation associated with cardiovascular disease, including cardiac remodeling, myocardial ischemia, and atherosclerosis." (PMID 34740366, 2021). "Signalling caused by PAMPs or their derivatives formed during processing may stimulate innate Toll-like receptors (TLR2 and TLR4), leading to strong immune reactions associated with inflammation, type 2 diabetes, atherosclerosis, and increased cardiometabolic risk factors." (PMID 34836203, 2021). "Thus, TLR4 inhibitors might be a novel treatment to decrease the risk of atherosclerosis induced by chronic stress." (PMID 34580342, 2021). "Additionally, genotyping of TLR4 variants (Asp299Gly and Thr399Ile) was employed to investigate whether genetic variants of TLR4 were associated with reduced inflammatory response and susceptibility for atherosclerosis among indigenous black CKD cohorts." (PMID 32649699, 2020). "Any genetic mutation within this pathway, especially in key genes like TLR4 and MyD88, could potentially alter the action of other components of the pathway so as to influence inflammatory reactions in the pathogenesis and progression of atherosclerosis." (PMID 26959040, 2016). "In order to evaluate whether pattern recognition receptors (PRRs) such as TLR-4 and CD14 contribute to atherosclerosis formation, we genotyped both study and control groups for the Asp299Gly and Thr399Ile polymorphisms of the TLR-4 gene and the C260T CD14 gene polymorphism." (PMID 29367560, 2016). "TLR4 is implicated in a diverse range of pathological processes associated with or induced by angiogenesis including autoimmune diseases such as psoriasis, diabetic retinopathy, thrombosis, and inflammatory disorders including arthritis and atherosclerosis and cancer." (PMID 25071774, 2014). "Although it has been reported that deficiency of TLR4 is associated with reduced atherosclerosis in mice and attenuated pro-inflammatory state in diabetic mice, it remains unknown whether treatment with TLR4 antagonists reduces atherosclerosis in non-diabetic and diabetic mice." (PMID 24667766, 2014). "CTRP4 deficiency promotes the development of atherosclerosis in ApoE‒/‒ mice, whereas CTRP4 supplementation attenuates atherosclerosis via binding and inhibition of RAGE and TLR4." (PMID 41705294, 2026). "miR-140-5p inhibits TLR4 mRNA expression through 3′UTR binding, thereby reducing macrophage lipid accumulation, oxidative stress, and apoptosis associated with atherosclerosis." (PMID 40861271, 2025). "The present study demonstrates that AT-I protects against nicotine-induced macrophage pyroptosis and atherosclerosis by inhibiting the TLR4/ROS/TXNIP/NLRP3 signaling pathway." (PMID 40422906, 2025). "The pro-inflammatory cytokine IFNγ and TLR4 stimuli are among key factors contributing to the onset and progression of atherosclerosis." (PMID 41155497, 2025). "D. desulfuricans has been reported to aggravate atherosclerosis by increasing intestinal permeability and activating the endothelial TLR4/NF-κB pathway in Apoe−/− mice." (PMID 40371102, 2025).